CXCL1 (C-X-C motif chemokine ligand 1)
Diseases named in the same sentence as CXCL1 in open-access papers (continued):
Sharing a sentence is not in itself a finding about the gene and the disease.
colon carcinoma (continued). "Knockout of CXCL1 in colon cancer cells significantly inhibited the growth of tumors in mice compared to that in the other groups." (PMID 36434686, 2022). "The result showed that overexpression of CXCL1 in colon cancer cells significantly promoted colon cancer growth, while knockout of CXCL1 in colon cancer cells inhibited colon cancer growth." (PMID 36434686, 2022). "In contrast, C646 treatment of mice with CXCL1-overexpressing colon cancer significantly inhibited tumor growth, suggesting the involvement of P300 in CXCL1-mediated bioactivity." (PMID 36434686, 2022). "In the present study, treatment of CXCL1-overexpressing colon cancer cells with C646 (an inhibitor of P300) led to inhibition of CXCL1 expression along with decrease in the protein level of p65 in the nucleus." (PMID 36434686, 2022). "CXCL1, an important cytokine that promotes colon cancer development, induces myeloid cell-mediated immunosuppression." (PMID 36434686, 2022). "HIF-2α also contributes to the recruitment of neutrophils to colon tumors, enhancing colon cancer progression through enhancing CXCL1 chemokine expression." (PMID 35574410, 2022). "CXCL1 expression in colon cancer is much greater than in normal colon tissue, according to previous research." (PMID 35958781, 2022). "The epithelial HIF-2α-induced CXCL1 transcription triggers a robust accumulation of neutrophils and promotes colon tumor progression through CXCR2 binding." (PMID 35954156, 2022). "In the present study, CXCL1 was found to activate the NF-κB pathway in colon cancer cells, which is consistent with previous reports." (PMID 36434686, 2022). "In the subsequent mouse model experiments, CXCL1 was found to promote the progression of colon cancer." (PMID 36434686, 2022). "Knockout of CXCL1 in colon cancer cells significantly inhibited the growth of colon cancer, while overexpression of CXCL1 showed the opposite result." (PMID 36434686, 2022). "We demonstrate that CXCL1 promotes the proliferation and migration of colon cancer cells and has a facilitative effect on tumor angiogenesis." (PMID 36434686, 2022). "A recent study reported that the colonic cancer microenvironment uses dendritic cells’ plasticity to support cancer progression by enhancing the release of the inflammatory chemokine CXCL1, which is consistent with our results." (PMID 33747044, 2021). "VEGFA secreted by colon cancer cells stimulated CXCL1 production by TAMs, which recruited CXCR2+ MDSCs to promote liver metastasis." (PMID 34527668, 2021). "In patients with colon cancer, the survival time of patients with higher levels of expression of CXCL1, 3, 8, 10, and 14 was longer than that of patients with lower expression." (PMID 34439306, 2021). "Clinically, the tissue microarray analysis of 276 patients with colon cancer indicated that CXCL1 played a vital role in the progression and metastasis of colon cancer." (PMID 32213179, 2020). "Our results showed that CXCL1, CXCL2, CXCL3, and CXCL11 were all upregulated in colon cancer compared with healthy tissues, and in the colon cancer group, a high level of CXCL1, CXCL2, CXCL3, and CXCL11 was correlated with better survival in TCGA or GEO." (PMID 32337262, 2020). "A recent study has shown that GABRR1 is significantly upregulated by the transcriptome of chemokine (C-X-C motif) ligand 1-(CXCL1) treated colon cancer cells." (PMID 31921812, 2019). "Studies in other cancers show that CXCL1 expression plays a role in regulating the invasive potential of colon carcinoma cells." (PMID 29887999, 2018). "Dendritic cells (DCs) of colon cancer patients were collected for phenotype and CXCL1 expression by flow cytometry and Luminex assays." (PMID 30115896, 2018). "To investigate the molecular mechanism of TADC-derived CXCL1 in colon cancer progression, we assessed the transcriptome of CXCL1-treated SW620 cells by next generation sequencing (NGS)." (PMID 30115896, 2018).
colon carcinoma (continued). "It has been shown that CpG oligodeoxynucleotides and a vascular disrupting agent induced the regression of colon tumors in mice, and this correlates with an increase in CXCL1 and neutrophil infiltration in tumors." (PMID 29983866, 2018). "Overall, overexpression of UEV1A alone in HCT116 cells is sufficient to activate NF-кB, which in turn upregulates CXCL1 expression to enhance colon cancer cell metastasis, and this phenomenon appears to be true in other colon cancer cells as well." (PMID 29662619, 2018). "We have demonstrated here that colon tumors from rats showed a rise of CXCL1, CXCL2 after LipA treatment." (PMID 29983866, 2018). "In conclusion, our results further support the role of TADCs and their secreted CXCL1 in colon cancer progression." (PMID 30115896, 2018). "We and others have reported that elevated levels of CXCL1 or IL8 in human colon cancer cells promotes tumorigenicity and are upregulated in human ulcerative colitis and colon cancer." (PMID 26104296, 2015). "Genetic downregulation of p38α in AOM/DSS-induced mouse colon tumors reduces tumor growth, which correlates with reduced levels of IL-6, IL-11, CXCL-1 and CXCL-2." (PMID 25890501, 2015). "In the three cases of colon cancer examined, the CXCL1 ISH signal was seen in a subset of stromal cells located towards the central ulcer of the lesion." (PMID 26208990, 2015). "Our finding that CXCL1 was also expressed by CRC myofibroblasts is consistent with its detection in the stroma of colonic tumor tissue microarrays." (PMID 26104296, 2015). "It is also shown that CXCL1 promotes colon cancer development through the activation of NF-κB/P300." (PMID 39408697, 2024). "However, further studies are required to identify the pathway by which CXCL1 leads to increased vascularity in colon cancer." (PMID 36434686, 2022). "Moreover, the IL6/JAK/STAT3 pathway has been found to upregulate CXCL1, CXCL2, CXCL3, and CXCL11 in patients with colon cancer, which was associated with prognosis." (PMID 35468892, 2022). "To further validate the promoting effect of CXCL1 on colon cancer growth in vivo, we transplanted three cell lines (MC38 WT, MC38CXCL1−/−, MC38CXCL1+/+) percutaneously at the right flank of C57BL/6J male mice and started assessing the tumor volume 1 week later." (PMID 36434686, 2022). "CXCL1 has been reported to activate NF-κB in other cancer types; however, whether CXCL1 can activate NF-κB in colon cancer has rarely been reported." (PMID 36434686, 2022). "We observed a positive correlation between CXCL1 and the number of tumor vessels in colon cancer." (PMID 36434686, 2022). "We examined the effect of CXCL1 on migration of colon cancer cells using Transwell assay." (PMID 36434686, 2022). "In conclusion, we demonstrated overexpression of CXCL1 in colon cancer tumors." (PMID 36434686, 2022). "Similarly, 11 genes were differentially expressed in colon cancer (CXCL1, 2, 3, 5, 8, 9, 10, and 11 were up-regulated, and CXCL11, 12, 13, and 14 were downregulated)." (PMID 34439306, 2021). "Colon cancer cells infected with F. nucleatum, through the bacterial surface adhesin Fap2, have been shown to produce interleukin 8 (IL-8) and C-X-C Motif Chemokine Ligand 1 (CXCL1), which stimulate the spread of malignant cells." (PMID 34523079, 2021). "We also used animal experiments to determine whether colon cancer increased CXCL1 expression in DCs in vivo." (PMID 30115896, 2018). "Moreover, CXCL1 is identified as a distinctly overexpressed gene in human colon cancers by microarray analyses and it promotes the growth and invasion of colon cancer cells in a mouse xenograft tumor model." (PMID 29662619, 2018).
colon carcinoma (continued). "Inflammatory chemokine CXCL1, present in large amounts in DCs isolated from colon cancer patients, and SW620-conditioned TADCs, enhance CSC characteristics in cancer, supported by enhanced anchorage-independent growth, CD133 expression and aldehyde dehydrogenase activity." (PMID 30115896, 2018). "The enhanced CXCL1 expression in DCs is also noted in mice transplanted with colon cancer cells." (PMID 30115896, 2018). "Indeed, experimental overexpression of UEV1A alone in HCT116 cells is sufficient to activate NF-кB, which in turn up-regulates the CXCL1 expression to enhance colon cancer cell metastasis." (PMID 29662619, 2018). "Cancer cells that overexpress CXCL1 and 2 by transcriptional hyper-activation or 4q21 amplification are primed for survival in metastatic sites and increased anchorage-independent growth of murine fibroblasts and human colon cancer cells." (PMID 29245915, 2017). "However, the immunosuppressive environment of tumors in AOM/DSS treated mice completely abolished the expression IL-6 and CXCL1, suggesting that colon cancer also affects the helminth-specific immune response." (PMID 28938014, 2017). "Moreover, the chemokine receptor CXCR-2 and its ligands CXCL-1 and CXCL-2 have been proposed to facilitate the growth of spontaneous and inflammation-associated colon tumors." (PMID 25890501, 2015). "Moreover, CXCL1 could regulate the infiltration of MDSCs in the premetastatic liver tissue in colon cancer xenografts, while inhibition of its chemokine receptor CXCR2 suppressed the recruitment of MDSCs in the PMN." (PMID 37210553, 2023). "We hypothesized that CXCL1 promotes the development of colon cancer through the NF-κB/P300 pathway." (PMID 36434686, 2022). "In addition, VEGF-A secreted by colon cancer cells could stimulate TAMs to produce CXCL1, which subsequently recruited MDSCs into the premetastatic sites to establish PMN, and in turn promoting liver metastasis." (PMID 32213179, 2020). "qPCR showed that LPS increased CXCL1, ELK1, ICAM1 and ZFAND5 mRNA levels, but decreased BCL2L1 and E2F1 mRNA levels in the colon cancer cells." (PMID 37705049, 2023). "LPS also increased COX2, CXCL1, ELK1, ICAM1, TNFSF10 and ZFAND5 but decreased BCL2L1, CYP19A1 and E2F1 mRNA levels in the colon cancer cells." (PMID 37705049, 2023). "Therefore, we hypothesized that CXCL1 promotes angiogenesis and colon cancer." (PMID 36434686, 2022). "CXCL1 and its receptor CXCR2 have been reported in colon cancer and gastric cancer and play an important role in metastasis." (PMID 34813418, 2022). "Several chemokines such as CXCL1, CXCL12, and CXCL2 as well as CXCL17 were involved in the development, growth, and progression of the colon cancer." (PMID 35607443, 2022). "Chen and colleagues found that CXCL1, CXCL2, and CXCL3 were all highly expressed in colon cancer tissues." (PMID 34269159, 2021). "CXCL1, CXCL2, CXCL3, and CXCL11 were upregulated in patients with colon cancer and significantly correlated with prognosis." (PMID 32337262, 2020). "The expression level of CXCL1 is an independent prognostic factor for both OS and DFS in patients with colon cancer." (PMID 32213179, 2020). "In our study, the increase of CXCL1 and CXCL2 both in rat model and patients with colon cancer correlates with neutrophil recruitment within tumors." (PMID 29983866, 2018). "TADCs increased colon cancer CSC properties, cell migration and EMT by producing CXCL1 in a paracrine fashion." (PMID 30115896, 2018). "The expression of CXCL1 and CXCL2 in human colon tumors has been described and there is a report that CXCL1 is highly expressed in poor invasive tumors." (PMID 29983866, 2018). "The current study demonstrated that in colon cancer, TADC-derived CXCL1 promotes expression of high levels of the PTHLH transcript and its protein, which are negatively correlated with relapse-free and overall survival rates in colon cancer." (PMID 30115896, 2018).
colon carcinoma (continued). "In contrast, CXCL1 and MMP9 are upregulated significantly in UEV1A-overexpressed HCT116 colon cancer cells." (PMID 29662619, 2018). "Reduced CXCL1 levels have been shown to result in decreased colorectal tumor growth and to suppress tumorigenic growth of K-RAS mutant colon cancer cells." (PMID 29245915, 2017). "This suggests that secreted CXCL1 and IL8 are derived from myofibroblasts under serum nutrient enriched condition and from human colon cancer epithelia under serum nutrient deprivation." (PMID 26104296, 2015). "For example the chemokine C-X-C motif ligand 1 (CXCL1) and its G protein-coupled receptor CXCR2 has been demonstrated in regulating growth and development of colon carcinomas via the COX-PGE2 signaling axis." (PMID 19819266, 2009). "Furthermore, qRT-PCR experimental results further confirmed that compared with normal colon epithelial cells, the expression levels of CCL22, CXCL1, CXCL8, and CXCL11 were upregulated in colon cancer cells." (PMID 38791448, 2024). "Moreover, WGP inhibited the expression of the chemokines CXCL1 and CXCL2, which are related to angiogenesis and dysplasia-carcinoma transition processes in colon cancers." (PMID 36713833, 2023). "In addition, CXCL1 has been reported to stimulate angiogenesis via the VEGF pathway, and it has even been suggested as a biomarker for patients suffering from colon cancer." (PMID 37175937, 2023). "Analysis of public data showed that CXCL1 driven oncogenes and mir-105 had a negative impact on the prognosis of colon cancer." (PMID 35958781, 2022). "The infiltration of CD4, CD8, and CD163 in tumor tissues after CXCL1 knockout was not significantly different from that in wild-type colon cancer tissues." (PMID 36434686, 2022). "Indeed, PGE2 stimulation of airway smooth muscle, endometrium, or colon cancer cells leads to increased production of VEGF, bFGF, or CXCL1 that, in turn, act on target endothelial cells to promote the angiogenesis." (PMID 34208772, 2021). "Analysis of publicly available data reveals CXCL1-driven oncogenes and miR-105 have a negative prognostic impact on the outcome of colon cancer." (PMID 30115896, 2018). "In addition to CCL2, CXCR2 ligands including CXCL1, CXCL2, CXCL3, and CXCL8 produced by CRC cells and neutrophils themselves were found to be responsible for recruitment of CXCR2+ neutrophils/PMN-MDSCs to colon tumors." (PMID 31681563, 2019). "We determine that the levels of CXCL1 and IL8 did not significantly affect overall survival in stage II and III human colon cancer, a finding supported by another group." (PMID 26104296, 2015).
prostate carcinoma (61 papers, 2008 to 2026). A carcinoma that arises from epithelial cells of the prostate gland. "It was reported that increased CXCL1 protein levels were associated with higher-grade stage in prostate cancer, advanced tumor stage and poorer prognosis in gastric cancer through VEGF signaling." (PMID 26506233, 2015). "Additionally, CXCL1 reduces fibulin-1 expression in prostate cancer cells and causes the activation of NF-κB, which forms a complex with histone deacetylase 1 (HDAC1)." (PMID 37108425, 2023). "Moreover, a recent study demonstrated that obese patients with prostate cancer have an increased expression of CXCL1 and its overexpression is linked to obesity-dependent tumor adipose stromal cells’ recruitment and, ultimately, promotes the progression of prostate cancer." (PMID 36836748, 2023). "An example of this is HL2401, a monoclonal antibody anti-human CXCL1 which inhibits the proliferation and migration of bladder and prostate cancer cells and inhibits the angiogenesis of the tested tumors." (PMID 40427171, 2025). "For example, taxanes cause a decrease in CXCR2 expression in metastatic castration-resistant prostate cancer, which reduces the action of CXCL1." (PMID 40427171, 2025). "The role of GRO expression in prostate cancer cells was revealed in the murine TRAMP-C2 cell model, lacking expression of CXCL8 and overexpressing CXCL1." (PMID 39594640, 2024). "Senescent prostate cancer cells secrete IL‐6, CXCL1 and CXCL2, which inhibit the activity of T cells, including both CD4+ T and CD8+ T cells, thereby promoting prostate tumour growth." (PMID 39270064, 2024). "The expression of CXCR2, the receptor for CXCL1, is higher in less aggressive prostate cancer lines." (PMID 37108425, 2023). "In androgen-independent (AI) PC-3 prostate cancer cells, curcumin has been reported to inactivate the NF-κB pathway and suppress the C-X-C motif chemokine ligand 1 (CXCL-1) and CXCL-2." (PMID 37176840, 2023). "The exposure of prostate cancer cells to CXCL1 increases the adhesion of these cells to type-I collagen." (PMID 37108425, 2023). "CXCL1 is produced by prostate cancer cells, as well as myofibroblasts and CAF that have lost TGF-β type II receptor (TβRII) expression." (PMID 37108425, 2023). "CXCL1 protein levels increased in high-grade malignancies, as well as higher-grade prostate cancer tumors." (PMID 36614235, 2023). "CXCL1 acts as a paracrine factor promoting prostate cancer metastasis through cross-talk among multiple cell types within the tumor microenvironment." (PMID 36836748, 2023). "CXCL1 shows weak stimulatory properties for prostate cancer cell proliferation, as shown by studies on PC-3 and DU 145 cell lines." (PMID 37108425, 2023). "Nevertheless, higher CXCL1 expression in prostate tumors is associated with a worse prognosis for the patient, which indicates an important function of CXCL1 in tumorigenic processes in prostate cancer." (PMID 37108425, 2023). "At the same time, in castration-resistant prostate cancer cells, the expression of CXCL1 is mediated by NF-κB2/p52, whose activity is elevated relative to less aggressive prostate cancers." (PMID 37108425, 2023). "For THP-1 prostate cancer co-cultures, a significant regulation of CXCL1, CXCL10, IL8, and VEGF was observed with plasma treatment." (PMID 32316245, 2020). "We further investigated the effect of CXCL1 and LCN2 on prostate cancer using in vivo and in vitro models, and explored the underlying signal transduction pathways." (PMID 31500632, 2019). "Here we report that FRG1 knockdown leads to p38 activation in prostate cancer cells affecting CXCL1 expression, which is well supported by previous studies, except the role of FRG1." (PMID 30975102, 2019). "With respect to prostate cancer, CXCL1 is known to affect cell migration and invasion via NFĸB/HDAC." (PMID 30975102, 2019). "Kuo’s group reported that CXCL1 activates the NF-κB/HDAC1 pathway in prostate cancer, and that NF-κB can act as an upstream regulator of CXCL144." (PMID 30158589, 2018).